HOTAIR (HOX transcript antisense RNA)
Diseases named in the same sentence as HOTAIR in open-access papers (continued):
Sharing a sentence is not in itself a finding about the gene and the disease.
lung cancer (continued). "For instance, elevated HOTAIR and reduced MEG3 have been shown to drive cisplatin resistance in lung cancer cells." (PMID 33803619, 2021). "Our results indicated that opposite effect of HOTAIR and miR‐34a‐5p on NSCLC cell proliferation and invasion and involvement in mediating the enhanced anti‐lung cancer effect of BBR and gefinitib." (PMID 32248643, 2020). "Depletion of HOTAIR weakens HOXA1 methylation by decreasing DNMT1 and DNMT3b expression and participates in chemoresistance in lung cancer." (PMID 33362860, 2020). "Our results showed that the regulation of miR‐34a‐5p‐ and HOTAIR‐mediated inhibition of EMT and subsequently growth and metastasis by the combination of berberine and gefitinib in human lung cancer." (PMID 32248643, 2020). "In summary, we find that HOTAIR can regulate HNRNPA1 expression through a ceRNA mechanism by sequester miR-149-5p, which post-transcriptionally targets HNRNPA1, thus promoting lung cancer progression." (PMID 33102210, 2020). "Our results showed that the regulation of miR‐34a‐5p‐ and HOTAIR‐mediated inhibition of EMT and subsequently growth and metastasis by the combination of BBR and EGFR‐TKI gefitinib in lung cancer cells." (PMID 32248643, 2020). "Our findings suggested that SM‐inhibited human lung cancer cell growth via inhibition of the PDPK1 and HOTAIR, and induction of miR‐214‐3p signalling axis." (PMID 31475459, 2019). "To date, only a few lncRNAs (including MALAT1, HOTAIR, H19, MEG3, GAS5, ANRIL, and SOX2OT etc.)have been reported to be dysregulated and functionally characterized in lung cancer and most of the studies were based on microarray expression data." (PMID 26862852, 2016). "HOTAIR levels were significantly higher in lung cancer cell lines than that in HBE (human bronchial epithelial cell), A549 was selected for further study for it’s one of lowest levels of HOTAIR in these cancer cells." (PMID 26658322, 2015). "Although the expression levels of MALAT1, HOTAIR, and AFAP1‐AS1 showed a statistically significant correlation with LNM in lung cancer patients according to the forest plots, the quality assessment tests demonstrated that the outcome for AFAP1‐AS1 is more reliable." (PMID 39725668, 2024). "Some LncRNAs including HOTAIR, MALAT1, NEAT1, and NNT‐AS1 have been involved in cisplatin resistance, through WNT and/or MAPK/Slug intracellular signaling pathways, as well as promoting malignancy in solid lung tumors, and lung cancer cell lines." (PMID 33433063, 2021). "Our study demonstrated that HOTAIR expression increased in NSCLC, and that the genotypes of rs920778 could be useful in the diagnosis and prognosis of lung cancer." (PMID 32394637, 2020). "The functional roles of HOTAIR and miR‐34a‐5p, and mechanistic analysis of their interplays with EMT signalling pathways in lung cancer, especially in mediating the synergistic effects of BBR and gefitinib remain largely unknown." (PMID 32248643, 2020). "Additionally, in Lung cancer cell lines (A549, H460, H1299, NCI-H460, HCC-827), HOTAIR regulates the expression of BECN1, phospho-ULK1, and the LC3II/I (MAP1LC3A / MAP1LC3B) ratio." (PMID 32438606, 2020). "Moreover, our results unveiled a synergistic effect of combination of BBR and gefitinib in the regulation of HOTAIR, miR‐34a‐5p and EMT, and lung cancer cell growth." (PMID 32248643, 2020). "More generally, the HOX cluster-embedded lncRNAs (HOX-lncRNAs) plays a significant role in the regulation of their adjacent coding genes and several HOX-lncRNAs, including HOTTIP, HOXA11-AS, HOTAIRM1, HOXA-AS3, HOXA10-AS, HOTAIR, and HAGLR, which are dysregulated in lung cancer." (PMID 32438606, 2020). "We showed that SM inhibited the growth of non‐small cell lung cancer (NSCLC) cells, which was enhanced in cells with silencing of long non‐coding RNA (lncRNA) HOX transcript antisense RNA (HOTAIR), while it overcame by overexpression of HOTAIR." (PMID 31475459, 2019).
lung cancer (continued). "Long noncoding RNAs (lncRNAs) such as HOTAIR and MALAT1 have been shown to be involved in the development of breast and lung cancer, however, role of lncRNAs in lymphoma is still unknown." (PMID 29113297, 2017). "HOTAIR-regulated EZH2-dependent methylation of non-histone substrates in lung cancer cells can be explored using a proteomic survey of the methylated proteins with or without inhibition of HOTAIR and/or EZH2." (PMID 25491133, 2014). "In breast, colon and liver cancer, the involvement of HOTAIR in cell growth has not been demonstrated, whereas HOTAIR promoted and reduced cell proliferation in pancreatic cancer and lung cancer, respectively." (PMID 24130837, 2013). "While the links of HOTAIR and miR‐34a‐5p to the EMT process have been reported, the functional roles of HOTAIR and miR‐34a‐5p, and their interactions with EMT signalling pathways in lung cancer, especially in mediating the synergistic effects of berberine and gefinitib remain largely unknown." (PMID 32248643, 2020). "Therefore, this study first used different analytical functions of GEPIA and UALCAN to explore the expression of HOTAIR in the prognoses of patients with LUAD and LUSC, together with identifying effective biomarkers of LUAD and LUSC that will provide strong evidence for lung cancer prognosis." (PMID 32394637, 2020). "We found that HOTAIR expression increased in NSCLC, and that the genotypes of rs920778 are protective factors in female patients and nonsmokers; this is useful for screening and prognosis for lung cancer." (PMID 32394637, 2020).
glioma (103 papers, 2015 to 2025). A benign or malignant brain and spinal cord tumor that arises from glial cells (astrocytes, oligodendrocytes, ependymal cells). "HOTAIR promotes malignant progression and poor prognosis in glioma patients, with its pro-oncogenic activity linked to cell cycle modulation." (PMID 41149459, 2025). "In conclusion, by “sponging” miR‐126‐5p, the lncRNA HOTAIR functions as a ceRNA, causing glioma cells to change their glutamine metabolism and upregulate the expression of GLS." (PMID 40567251, 2025). "Oncological research studies have confirmed the pathogenic functions of HOTAIR in multiple cancer types, such as gliomas and proposed it as a pro-oncological lncRNA." (PMID 38682637, 2024). "In consistence, a strong positive association of HOTAIR expression with glioma grades was observed in Chinese clinical cases after adjusting for gender and age." (PMID 38366205, 2024). "Serum-derived exosomes as peripheral prognostic and diagnostic platforms for gliomas, specifically for the evaluation of HOTAIR expression have also been proposed in recent studies." (PMID 38366205, 2024). "More recently, hyperactivation of HOTAIR in glioma pathogeneses has been shown to be associated with histone H3K27-methylation-mediated transcriptional repression of peroxisome proliferator-activated receptor alpha (PPARα)." (PMID 38366205, 2024). "On the other hand, lncRNAs such as MALAT1 and HOTAIR have been implicated as oncogenes, promoting glioma cell growth, invasion, and angiogenesis." (PMID 37444408, 2023). "As a well-studied lncRNA, HOTAIR has been associated with several malignancies, such as gliomas, thyroid, liver, lung, breast, and colorectal cancers." (PMID 35359879, 2022). "(2018) reported the regulation function of HOTAIR on glutaminase (GLS) expression through sponging miR-126-5p in a competing endogenous RNA axis HOTAIR/miR-126-5p/GLS that is implicated in glioma progression." (PMID 35912242, 2022). "In summary, our data demonstrated that HOTAIR activates the implicated in inflammatory responses NF-κB pathway in mesenchymal glioma cells and promotes immune escape via an aberrant PD-L1 expression." (PMID 34887871, 2021). "HOX transcribed antisense RNA (HOTAIR) is overexpressed in glioma and associated with the proliferation and periodic progression of this tumor." (PMID 34540687, 2021). "Circulating levels of HOTAIR have also been described in glioma patients and are associated with a poor prognosis." (PMID 34576322, 2021). "HOTAIR aberrant expression has been abundantly described in glioma tumors and closely associated with glioma grade and poor prognosis." (PMID 34576322, 2021). "High levels of HOTAIR were associated with higher grades of glioma, particularly IDH wild-type cases." (PMID 29644006, 2018). "The mechanisms underlying elevated HOTAIR expression in glioma remain to be investigated, and a study in breast cancer hints at both transcription and posttranscriptional regulations." (PMID 30116729, 2018). "For example, the CT variant of the functional single nucleotide polymorphism rs12826786 in HOTAIR locus was associated with its higher intratumoral expression in glioma, and would require further addressing." (PMID 29644006, 2018). "Overall high expression of HOTAIR in our glioma samples indicates its association also with glioma development and was already found essential for glioblastoma proliferation." (PMID 29138748, 2017). "The well-studied lncRNA HOTAIR is also upregulated in glioma cells, its expression is closely associated with glioma grade and poor prognosis and glioma cell growth is reduced following its depletion." (PMID 28423669, 2017). "The HOTAIR mRNA levels were significantly up-regulated in glioma samples in comparison with normal brain tissues, and the upregulation of HOTAIR associated with glioma malignancy." (PMID 27121316, 2016). "The expression patterns of HOTAIR are closely associated with glioma staging, and its increased expression with tumor progression." (PMID 26230711, 2015).
glioma (continued). "In this study, we aim to clarify the mechanism underlying HOTAIR-mediated regulation of cell cycle progression in glioma cells, as well as the function of PRC2 and LSD1 in this process." (PMID 25428914, 2015). "Survival analysis of Chinese Glioma Genome Atlas (CGGA) patient data indicated that high HOTAIR expression was associated with poor outcome in GBM patients." (PMID 25823657, 2015). "We recently discovered that HOTAIR is a cell cycle-related lncRNA in human glioma, and its expression is closely associated with glioma staging and poor prognosis." (PMID 25428914, 2015). "Functional studies have demonstrated that loss of HOTAIR would render glioma cells more susceptible to cell-cycle arrest, with retarded tumor growth and reduced tumor cell invasiveness." (PMID 26230711, 2015). "Another molecular sponge of HOTAIR implicated in glioma pathogenesis is miR-326." (PMID 38366205, 2024). "The objective of this timely review is not only to outline the multifaceted pathogenic roles of HOTAIR in the development and pathophysiology of gliomas and brain cancers, but also to delineate the research findings implicating it as a critical regulator of overall brain pathophysiology." (PMID 38366205, 2024). "Interestingly, HOTAIR-miR-148b-3p signaling has also been implicated in the dysregulation of blood-tumor barrier in gliomas via the mediation of the upstream stimulatory factor 1 (USF 1) pathway." (PMID 38366205, 2024). "The levels of HOTAIR in tumor samples are much higher than in normal samples, and this research indicated that HOTAIR might be utilized as a prognostic and diagnostic biomarker for glioma." (PMID 34722277, 2021). "Such as HOTAIR was reported to significantly associated with the invasiveness of gliomas." (PMID 32523951, 2020). "While some oncogenic functions of HOTAIR have been reported in glioma, the underlying mechanisms responsible for HOTAIR activation in such a devastating disease have remained unknown thus far." (PMID 29644006, 2018). "Thus, our work provides novel insights on HOTAIR’s transcriptional regulators, widening our understanding of the HOTAIR-associated mechanisms of aggressiveness and malignancy in gliomas." (PMID 29644006, 2018). "The expression level of HOTAIR was positively associated the grades of the glioma specimens." (PMID 28410200, 2017). "For example, the well-studied HOTAIR, a lncRNA highly expressed in breast cancer that participates mainly in the chromatin remodeling process, was found to be associated with the biogenesis, development and differentiation of gliomas." (PMID 28293170, 2017). "In addition, HOTAIR is closely associated with glioma grade, as well as a critical regulator of cell cycle progression." (PMID 27121316, 2016). "Thus, downregulation of HOTAIR was reported to normalization of HK-2 mRNA and protein expressions, and increased temozolomide susceptibility in vitro, in U87 cells, as well as in vivo, in immune-compromised with mice subcutaneous glioma cell xenograft." (PMID 38366205, 2024). "In addition to gliomas, HOTAIR has been implicated in the pathogeneses of other brain tumours." (PMID 38682637, 2024). "However, the precise mechanism underlying how HOTAIR regulates cell cycle progression of glioma cells remains largely unknown." (PMID 25428914, 2015). "Despite the fact that polycomb repressive complex 2 (PRC2) and lysine specific demethylase 1 (LSD1) have been shown to be functional targets of HOTAIR, it is still unclear how HOTAIR controls the progression of the glioma cell cycle." (PMID 41439968, 2025). "Research studies have revealed that HOTAIR functions as a “sponge” for miR‐126‐5p, enhancing glutamine metabolism in gliomas." (PMID 40567251, 2025). "In general, the presented study provided an overview of the association of COL4A family members with glioma progression and present a COL4A-H19/HOTAIR-miR148a/miR222-HMGA2 axis in glioma established by a COL4A-related ceRNA interaction network." (PMID 40351420, 2025).
glioma (continued). "After analyzing the existing literature, we can state that the most reliable data seem to be related to the action of certain lncRNAs in gliomas, such as HOTAIR, NEAT1, MEG3, and MALAT1." (PMID 41149459, 2025). "In glioma, the oncogenic lncRNA HOTAIR can promote the occurrence and metastasis of tumors and is highly expressed in glioma, colorectal cancer and lung cancer." (PMID 40821785, 2025). "Previous work supports a functional role for HOTAIR rs12826786: in glioma tissue, the CT genotype shows higher HOTAIR expression than TT, indicating a cis-eQTL-like effect." (PMID 41463069, 2025). "HOTAIR regulatory elements function as silencers to modulate glioma cell sensitivity to TMZ through long-range regulation of the targets, CALCOCO1 and ZC3H10." (PMID 41149459, 2025). "On the other hand, HOTAIR, a lncRNA, regulates tumor progression by participating in chromatin remodeling and promoting the proliferation of gliomas." (PMID 39465690, 2025). "While HOTAIR expression is typically low in normal brain tissue, it is significantly upregulated in gliomas, particularly in temozolomide-resistant GBMs." (PMID 41149459, 2025). "As already discussed, elevated expression of HOTAIR is a potent indicator of high grade/severity, poor prognosis, and reduced survival in gliomas." (PMID 38366205, 2024). "This ability of HOTAIR to act as a ceRNA allows it to abolish availability of target miRNA species for regulating the translation of downstream mRNAs (also see “HOTAIR-Mediated Trans-Silencing of miRNAs in Glioma Pathogeneses” section)." (PMID 38366205, 2024). "Multiple anti-glioma therapeutic agents/strategies which act by repressing the expression of HOTAIR have been proposed." (PMID 38366205, 2024). "Pharmacological agents have been shown to be rendered severely ineffective because of the hyperactivation of HOTAIR signaling in gliomas." (PMID 38366205, 2024). "This contributes as another interesting facet of HOTAIR-dependent pro-tumorigenic gene expressional effects in gliomas." (PMID 38366205, 2024). "MiR-218-phosphodiesterase 7A (PDE7A) signaling axis is another mediator linking hyperactivation of HOTAIR and glioma pathogeneses." (PMID 38366205, 2024). "Several recent in vivo and in vitro studies have proposed HOTAIR as a tremendous biotarget for anti-glioma therapies." (PMID 38366205, 2024). "For example, the abnormally high expression of HOTAIR in glioma can significantly reduce the survival time of patients and can be used as a target for diagnosis and treatment." (PMID 38552216, 2024). "In silico (and combinatorial) studies have been instrumental in our understanding of the multimodal tumour-promoting roles played by HOTAIR in gliomas." (PMID 38682637, 2024). "MiR-301a-3p and its downstream target, pro-tumorigenic transcription factor, Fos like 1 (FOSL 1) represent another set of mediators of HOTAIR’s actions in glioma pathogenesis." (PMID 38366205, 2024). "Pharmacological studies have also been evaluated/directed to target hyperactivated HOTAIR signaling in gliomas." (PMID 38366205, 2024). "This information was used for design of a combinatorial therapeutic strategy of fenofibrate-mediated PPARα activation and siRNA-mediated HOTAIR repression to robustly retard glioma proliferation and invasion." (PMID 38366205, 2024). "Further, robust association of the expression of HOTAIR with the levels of homeobox protein HOXA9 was observed in glioma tissues, particularly from clinical subjects of higher-grade gliomas." (PMID 38366205, 2024). "Lastly, knockdown of HOTAIR under in vivo settings in glioma harboring mice was shown to robustly reduce tumor burden." (PMID 38366205, 2024). "In their follow-up study, the research group identified programmed death ligand 1 (PDL-1)-mediated activation of pro-inflammatory nuclear factor kappa B (NF-κB) signaling as a critical HOTAIR-based therapeutic target against immune tolerance of gliomas." (PMID 38366205, 2024).